IL1A (interleukin 1 alpha)
Diseases named in the same sentence as IL1A in open-access papers (continued):
Sharing a sentence is not in itself a finding about the gene and the disease.
purpura (1 paper, 2019). A small blood vessel hemorrhage into the skin and/or mucous membranes. "Although purpura and petechiae are seen in skin, microvessel leakage occurs systemically and thus any local source of p33 IL-1α could be activated." (PMID 30926232, 2019).
radicular cysts (1 paper, 2018). "We found that the expression levels of IL-1α and IL-1β in the radicular cyst and normal control groups were very low; the average expression levels of IL-1β in those two groups were only 0.0017 and 0.0016 μg/mg total protein, respectively." (PMID 30012121, 2018).
retinal detachment (1 paper, 2024). An eye emergency condition which may lead to blindness if left untreated. "IL-1α is an early marker of inflammation and cell injury, and patients with retinal detachment have increased IL-1β levels in the subretinal fluid." (PMID 38530532, 2024).
retinitis (1 paper, 2021). Inflammation of the retina. "By comparison, retinitis-susceptible MCMV-infected eyes of mice immunosuppressed by corticosteroid treatment also showed significant intraocular increase in IL-1a production, albeit to a lesser extent than that observed for MCMV-infected eyes of MAIDS mice." (PMID 34358000, 2021). "As predicted, retinitis-susceptible MCMV-infected eyes of MAIDS mice at 3 days after intraocular infection showed dramatic increases in IL-1a mRNA and protein amounts when compared with retinitis-resistant MCMV-infected eyes of healthy mice that showed minimal IL-1a production." (PMID 34358000, 2021). "Our findings, therefore, suggest a role for the alarmin IL-1a in the pathogenesis of MCMV retinitis in animals immunosuppressed by two distinct mechanisms, drug-induced immunosuppression and retrovirus-induced immunosuppression." (PMID 34358000, 2021).
sarcoma (1 paper, 2012). A usually aggressive malignant neoplasm of the soft tissue or bone. "IL1a (mRNA) andIL1β (both mRNA and protein) were increased in all three forms of parental as well as bystander senescence in normal diploid BJ fibroblasts, but not in drug-induced U2OS (sarcoma) bystander senescent cells." (PMID 23385065, 2012).
Sciatica (1 paper, 2024). Pain in the lower back and hip radiating in the distribution of the sciatic nerve. "Conversely, there is a negative correlation between sciatica and Interleukin-1-alpha levels (p = 0.029, OR = 1.67E−05, 95% CI =8.79E−10–0.318), Interleukin-20 levels (p = 0.007, OR = 1.59E−06, 95% CI =8.95E−11–0.028), and Interleukin-33 levels (p = 0.029, OR = 7.62E−06, 95% CI =1.86E−10–0.312)." (PMID 39015317, 2024).
scleritis (1 paper, 2023). Inflammation of the sclera. "Moreover, histocompatibility complex (MHC), TNF, IL1A, IL1β, IL2, IFNγ, and TNF were widely present in the top five disease signaling pathways, suggesting that these genes may be involved in the development of scleritis." (PMID 37063831, 2023).
Senile plaques (1 paper, 2014). Senile plaques are extracellular deposits of amyloid in the gray matter of the brain. "IL1A, IL1B, IL2, IL8, IFNγ, and TNFα have been found to be associated with senile plaques." (PMID 25197660, 2014).
Shock (1 paper, 2025). The state in which profound and widespread reduction of effective tissue perfusion leads first to reversible, and then if prolonged, to irreversible cellular injury. "Since proinflammatory cytokine overproduction is indicative of sepsis, we evaluated the levels of TNF‐α, IFN‐γ, IL‐1α, IL‐1ß, IL‐6, IL‐10, IFN‐ß, IL‐17A, IL‐23, IL‐27, MCP‐1, IL‐12p70, and GM‐CSF in the serum at 16 h after LPS‐induced septic shock." (PMID 39482884, 2025).
sialoadenitis (1 paper, 2024). "Moreover, IL-1α and IL-1β have been detected in the acinar and ductal cells of the minor salivary glands of patients with SS and sialoadenitis." (PMID 38999930, 2024).
sleep disorder (1 paper, 2024). A change from the patient's baseline sleeping pattern, in the hours slept and/or an alteration/dysfunction in the stages of sleep. "Certain cytokines, including IL-6, IL-1α, and tumor necrosis factor (TNF-α), exhibit notable circadian oscillations when they enter the brain, leading to sleep disorders." (PMID 39418274, 2024).
sleeping sickness (1 paper, 2019). "This study revealed that one SNP (rs1800794) of IL1A and one VNTR (rs2234663) of IL1RN were associated with an increased risk to be infected by T. b. gambiense and develop HAT in inhabitants of sleeping sickness foci of southern Cameroon." (PMID 30908482, 2019). "The minor allele T and the genotype TT of SNP rs1800794 in IL1A as well as the genotype 1A3A of IL1RN rs2234663 VNTR seem to increase the risk of getting Trypanosoma brucei gambiense infections and develop sleeping sickness in southern Cameroon." (PMID 30908482, 2019). "This study revealed that one SNP rs1800794 of IL1A and one VNTR rs2234663 of IL1RN were associated with the increased risk to be infected by Trypanosoma brucei gambiense and develop sleeping sickness in southern Cameroon." (PMID 30908482, 2019). "Results of this study have shown that the genotype (TT) and minor allele (T) of IL1A gene and the genotype 1A3A VNTR of IL1RN are associated with an increased risk of getting T. b. gambiense infections and develop sleeping sickness in major ethno-linguistic groups of the Cameroonian population." (PMID 30908482, 2019).
small artery occlusion (1 paper, 2013). "However, data about the relationship between the IL-1α (C-889T) polymorphisms and the risk of IS classified by TOAST criteria (especially for small-artery occlusion (SVD) and cardioembolism (CE)) is limited in China." (PMID 24063019, 2013).
squamous cell tumors of the (1 paper, 2025). "The study by Douglas Hanahan and colleagues found that squamous cell tumors of the cervix and skin, driven by Human Papillomavirus type 16 (HPV16), release four immunomodulatory factors ‒ IL-1α, IL-1β, IL-33, and IL-36β ‒ into the bloodstream." (PMID 41418390, 2025).
subarachnoid hemorrhage (1 paper, 2014). A serious neurological disorder characterized by intracranial hemorrhage into the subarachnoid space. "We have reported recently that IL-1α-dependent inflammation worsens outcome in a rat model of subarachnoid hemorrhage, a devastating brain injury for which there are limited clinical options." (PMID 24790078, 2014).
synovitis (1 paper, 2019). Inflammation of a synovial membrane. "A recent phase II clinical trial of the anti-IL-1α/β dual variable domain immunoglobulin lutikizumab (ABT-981) in patients with knee OA and synovitis showed limited improvement in the WOMAC pain score and no improvement in synovitis." (PMID 31885861, 2019).
testicular cancer (1 paper, 2022). A primary or metastatic malignant neoplasm that affects the testis. "No studies were found about these specific variants in testis or these genes in testicular cancer, but the role of IL1A, NFKB1 and XRCC1 have been reported in Sertoli cells and other essential factors for spermatogenesis." (PMID 35678683, 2022).
testicular disease (1 paper, 2021). "In testicular-inflammation, cytokines such as TNF-α, IL-1α and IL-1β are produced in significant levels, and are particularly known to aggravate testicular disease progression, and subsequent death." (PMID 33565293, 2021).
thymoma (1 paper, 2025). A neoplasm arising from the epithelial cells of the thymus. "At least in APECED and thymoma, the development of cytokine autoantibodies is not limited to IFNs as they develop autoantibodies to other cytokines including IL-17A, IL-17F, IL-22, IL-12, and IL-1A." (PMID 40304722, 2025).
thyroid tumor (1 paper, 2015). A benign or malignant neoplasm affecting the thyroid gland. "On the other hand, thyroid tumor cells may actively participate in leukocyte recruitment, as RET oncogenic activation induces upregulation of the pro-inflammatory interleukins IL1α and IL8 in vitro." (PMID 26536459, 2015).
tic disorder (1 paper, 2024). Disorders characterized by recurrent TICS that may interfere with speech and other activities. "Finally, we compared children with tic disorders and control children in terms of cytokine expression (i.e., IL-1α, IL-1β, TNF-α, IL-6, TGF-β, IL-17, and IL-4) using qRT-PCR." (PMID 38956051, 2024).
tongue cancer (1 paper, 2025). A malignant neoplasm affecting the tongue. "Among the OSCC lines, HSC3 exhibited the highest IL-1α expression levels, whereas UM-SCC6 cells had the lowest, despite both being derived from tongue cancers." (PMID 40940885, 2025).
uterine disease (1 paper, 2020). "As both IL-1α and IL-1β have been shown to recruit different innate cells—accumulation of IL-1α correlated with the infiltration of neutrophils, and the expression of IL-1β correlated with later migration of macrophages, this could have important consequences for uterine disease pathogenesis." (PMID 33106520, 2020). "In agreement with previous literature by us and others, significant upregulation of genes encoding the potent Interleukin-1 family of inflammatory cytokines including IL1A and IL1B were detected signifying an exacerbation of inflammation in cows which subsequently develop clinical uterine disease." (PMID 33106520, 2020).
venous ulcers (1 paper, 2025). "Additionally, a recent study showed that patients with venous ulcers of the lower limbs had higher expression of pro-inflammatory cytokines such as tumor necrosis factor (TNF)-α and IL-1α in peripheral blood mononuclear cells than controls." (PMID 40103929, 2025).
viral hepatitis (1 paper, 2012). An acute or chronic inflammation of the liver parenchyma caused by viruses. "Elevated serum levels of IL-1α and IL-1β have been correlated with the impairment of hepatocytes, since they were reported to be present only in the acute and not in the recovery phase of viral hepatitis." (PMID 22384080, 2012).
visceral leishmaniasis (1 paper, 2016). A severe form of leishmaniasis characterized by irregular bouts of fever, substantial weight loss, swelling of the spleen and liver, and anemia (which may be serious). "Indeed, IL-1α-/- mice were more resistant than IL-1β-/- mice in the experimental visceral leishmaniasis model." (PMID 27501956, 2016). "The observed anti-inflammatory activity of Ole through repression of IL-1β gene seems to be very important in the first steps of experimental visceral leishmaniasis, since IL-1β was found to be in greater necessity for CD4+ polarization to the Th2 phenotype than IL-1α." (PMID 27501956, 2016).
visual disorders (1 paper, 2016). "Eight positively selected genes within the tarsier lineage were implicated in several diseases associated with eye development and visual disorders (BBS2, BFSP2, IDUA, IL1A, IMPG1, RGR, SRD5A3 and TMC8)." (PMID 27708261, 2016).
tumor (660 papers, 1990 to 2026). "Ligand-receptor pairs linked to high-risk tumors, including IL1A_IL1RAP, COL5A1_ITGB1, APP_NCSTN, PLAU_ITGA5, AGRN_ITGB1, and LAMC2_ITGA6, were found to be particularly enriched in tumor regions." (PMID 40021759, 2025). "Although encoded by separate genes, IL-1A and IL-1B exhibit identical biological functions, promoting inflammation and tumor progression." (PMID 40141426, 2025). "IL-1α and IL-1β also recruit and polarise tumour-associated macrophages and myeloid-derived suppressor cells, reinforcing an immunosuppressive microenvironment." (PMID 41465261, 2025). "IL-1α deficiency in TNBC leads to a significant decrease in tumor growth in immunocompetent mice, probably due to a reduction in inflammation and modulation of immune cells in the TME." (PMID 38612760, 2024). "Due to its unique properties and possibility to be active as an intracellular, membrane-associated, and secreted molecule, IL-1α can produce both pro- and anti-tumor effects." (PMID 38612760, 2024). "Our results suggest that tumor-associated IL-1α is involved in TNBC progression in mice by modulating the interplay between immunosuppressive pro-inflammatory cells vs. antigen-presenting and cytotoxic cells." (PMID 38612760, 2024). "Consistently, Il1b and Il1a expressions were significantly decreased in the tumor tissue of CCR2-deficient mice compared to WT mice, further corroborating that monocytes and monocyte-derived macrophages are the major source of IL-1 ligands in the colon TME." (PMID 39030280, 2024). "Membrane‐associated IL‐1α enhances the immunogenicity of tumour cells, Monitoring the immune response in tumours and encouraging their shrinkage." (PMID 39602465, 2024). "Inhibition of NK cell activation is associated with IL-1α released from tumor tissues, which also attenuates the killing ability of CD8+ T cells; moreover, IL-1α released from tumors recruits MDSC in the tumor microenvironment and promotes HCC development." (PMID 38426090, 2024). "IL-1α has been implicated in tumor-promoting activities, including tumor dedifferentiation and lymphangiogenesis." (PMID 38403820, 2024). "Knockout of IL-1α in 4T1 cells modified expression of multiple genes, including downregulation of cytokines and chemokines involved in the recruitment of tumor-associated pro-inflammatory cells." (PMID 38612760, 2024). "Overall, these results demonstrate that tumor-associated IL-1α leads to more intensive recruitment of immature suppressive myeloid cells, which secrete pro-inflammatory cytokines and support tumor progression." (PMID 38612760, 2024). "To assess if IL-1α deficiency in tumor cells affects tumor progression in mice, we created IL-1α knock-out 4T1 cells (4T1 IL-1α KO) using the CRISPR/Cas9 approach." (PMID 38612760, 2024). "In another preclinical study of colorectal cancer (CRC), upon irradiation, tumor-derived interleukin1α (IL-1α) mediated polarization of cancer-associated fibroblasts (CAFs) towards a pro-inflammatory pro-tumorigenic phenotype." (PMID 37170098, 2023). "We found the loss of Il1b prolongs survival while the loss of Il1a shortens survival of tumor-bearing mice." (PMID 37733448, 2023). "To demonstrate that IL-1α antagonizes the tumor-promoting effects of IL-1β, we generated tumors in WT;Ntv-a and Il1a–/–;Ntv-a: loss of Il1a resulted in accelerated tumor growth, which was the opposite of our observation in Il1b-deficient mice." (PMID 37733448, 2023). "Results showed that CPH:SA‐based IL‐1α‐MPs generated a slow and sustained systemic release of IL‐1α resulting in reduced toxicity (weight loss, cytokine storm, and hypotension) compared to free IL‐1α in tumor‐bearing mice." (PMID 37206237, 2023). "CPH:SA‐based IL‐1α‐MPs generated a slow and sustained systemic release of IL‐1α resulting in reduced weight loss, systemic inflammation, and hypotension accompanied by an adequate anti‐tumor immune response in HNSCC‐tumor bearing mice." (PMID 37206237, 2023).
tumor (continued). "In tumor models of fibrosarcoma and lymphoma, IL-1α overexpression was associated with tumor regression, mainly through the accumulation of intratumoral CD8+ cells." (PMID 35743911, 2022). "IL‐1α is also implicated in tumour vascularization by promoting the expression of vascular endothelial growth factor (VEGF) in endothelial cells." (PMID 35344301, 2022). "The activation of hypoxia signaling increases the expression of adipokines, especially the pro-inflammation adipokines (including CCL2, CXCL8, CXCL10, IL-18, IL-1α and Oncostatin M), which is involved in the recruitment of tumor-associated immune cells." (PMID 35350384, 2022). "We first analyzed the mRNA expression levels of damage-associated molecules (HMGB1, HSP60, HSP70, S100A8, IL-1A, IL-33) in 11 canine tumor cell lines." (PMID 33875721, 2021). "Taken together these data suggest that tumor tissues are characterized by high levels of caspase-4 and IL-1α which are associated to lower survival rate of NSCLC patients." (PMID 33187551, 2020). "IL‐1ra competitively blocks the pro‐inflammatory actions of IL‐1α and IL‐1β at the receptor level, which have been implicated in tumor growth." (PMID 33207085, 2020). "For example, in the tumor microenvironment, the cell-surface or secreted form of IL-1α is associated with anti-tumor responses, and NK cells are important cytotoxic cells in the immune system and can recognize and kill cancer cells." (PMID 33251135, 2020). "Oncogenic BRAF, through decreased MITF expression and enhanced IL-1α and IL-1β secretion, triggers PD-L1 and PD-L2 expression in tumor-associated fibroblasts which also contributes to suppression of tumor-infiltrating T cell function." (PMID 33276788, 2020). "An increased proportion of ILC2s have been also found in pancreatic adenocarcinoma where tumor cells and tumor cell-conditioned macrophages produce IL-1α and IL-1β favoring TSLP secretion by cancer-associated fibroblasts." (PMID 33233582, 2020). "High levels of IL-1α expression in cancers have also been linked to tumor dedifferentiation and lymphangiogenesis." (PMID 31231372, 2019). "Together with IL-1β, IL-1α, encoded by IL1A (interleukin 1 alpha), is defined as an “alarm cytokine” that belongs to IL-1 cluster and plays dual roles in malignant tumour progression." (PMID 30819119, 2019). "In HNSCCs, gene expression, tumor cell secretion, and circulating levels of IL-1α have all been associated with tumor progression and distant metastasis." (PMID 31320902, 2019). "In this cancer model, early activation of K-Ras through mutation induces IL-1α secretion and p62 feed-forward loops, which further lead to constitutive NF-κB activation, in an autocrine manner, enhancing tumor development, progression, and invasiveness." (PMID 31557902, 2019). "In contrast, IL-1α acted as a key mediator of immune surveillance; tumor cell lines derived from IL-1α-deficient mice showed reduced invasiveness when transplanted in wild-type hosts, demonstrating a lack of tumor editing in its absence." (PMID 30150983, 2018). "Tumor GM-CSF and IL-1α which were negatively associated with muscle weight and TFBW both had weak positive association with atrophy related gene expression." (PMID 30513792, 2018). "The end targets of this pathway, IL-6, IL-1α and IL-1β, and IL-8 cytokines, presented increased expression in the mesenchymal subtype, and they have also been associated to tumor malignancy and tumor cell migration." (PMID 29912993, 2018). "Loss of tumor editing in IL-1α-deficient mice was attributed to impaired NK cell maturation and a suboptimal killing capacity of effector immune cells resulting in reduced tumor editing." (PMID 30150983, 2018). "Recently, a report showed BMP-6 stimulates tumor-associated macrophages to produce IL-1α through a crosstalk between Smad1 and NF-kB1." (PMID 28068414, 2017). "IL1α is another member of inflammatory cascade which has been found to be associated with the tumor development and cancer cells metastasis." (PMID 26682000, 2016).